TMEM44 (transmembrane protein 44)
Synonyms: DKFZp686O18124
Tractability: Antibody: UniProt predicts a signal peptide or a membrane-spanning region.
Gene: Protein-coding gene on chromosome 3 (194,587,673 to 194,633,689, reverse strand). Ensembl gene ENSG00000145014.
Subcellular location: Membrane
Subcellular location (Human Protein Atlas): Cytosol
Gene Ontology:
Molecular function: basic amino acid transmembrane transporter activity
Biological process: basic amino acid transmembrane transport
Cellular component: lysosomal membrane; membrane
Genetic constraint (gnomAD): Loss-of-function variants: 40 observed, 39.72 expected, observed/expected ratio (o/e) 1.01, 90% interval 0.78 to 1.31. The synonymous counts are far from expectation, so gnomAD's model fits this gene poorly and the ratio says little. Missense variants: 528 observed, 478.08 expected, observed/expected ratio (o/e) 1.1, 90% interval 1.03 to 1.19. Synonymous variants: 258 observed, 203.23 expected, observed/expected ratio (o/e) 1.27, 90% interval 1.15 to 1.41.
Homologues: Orthologues: macaque TMEM44 (96% identical), chimpanzee TMEM44 (89% identical), pig TMEM44 (84% identical), mouse Tmem44 (78% identical), rat Tmem44 (78% identical), rabbit TMEM44 (74% identical), guinea pig TMEM44 (53% identical), tropical clawed frog tmem44 (39% identical), zebrafish tmem44 (26% identical), Caenorhabditis elegans laat-1 (14% identical). Paralogues in human: SLC66A1 (17% identical).
Diseases named in the same sentence as TMEM44 in open-access papers:
TMEM44 is named in the same sentence as 9 diseases in open-access papers, as found by Europe PMC text mining. Sharing a sentence is not in itself a finding about the gene and the disease. The quoted sentences say what the papers report.
atrial fibrillation (1 paper, 2021). A disorder characterized by an electrocardiographic finding of a supraventricular arrhythmia characterized by the replacement of consistent P waves by rapid oscillations or fibrillatory waves that vary in size, shape and timing and are accompanied by an irregular ventricular response. "Trait associations were found for five loci: the SNV at TMEM44 was associated with diastolic blood pressure, SLC27A6 with red cell distribution, NKX2–5 with heart rate and atrial fibrillation, and finally NUFIP2 with mean platelet volume." (PMID 34274964, 2021).
glioma (1 paper, 2022). A benign or malignant brain and spinal cord tumor that arises from glial cells (astrocytes, oligodendrocytes, ependymal cells). "TMEM44 is an integral component of membrane proteins, and previous studies demonstrated that upregulated lncRNA TMEM44-AS1 might promote glioma progression and was correlated with 5-FU resistance in gastric cancer." (PMID 36463181, 2022).
renal clear cell carcinoma (1 paper, 2024). "Consequently, there is a knowledge gap regarding TMEM44, prompting us to investigate its potential significance across various tumors through a pan-cancer analysis, with a specific emphasis on kidney clear cell carcinoma (KIRC)." (PMID 37561335, 2024). "Therefore, investigating whether VSX1 influences the progression of renal clear cell carcinoma through downstream TMEM44 warrants further investigation." (PMID 37561335, 2024). "Additionally, overexpression of VSX1 has been shown to increase the activity of TMEM44, FKBP10, and TRIB3, and enhance the growth of renal clear cell carcinoma." (PMID 37561335, 2024).
cancer (2 papers, 2022 to 2024). A tumor composed of atypical neoplastic, often pleomorphic cells that invade other tissues. "Subsequently, we focused on KIRC and found a significant correlation between TMEM44 expression and this particular cancer type." (PMID 37561335, 2024). "Pan-cancer analysis of progression-free survival (PFS) revealed that TMEM44 was an independent predictor in ACC, ESCA, KIRC, LIHC, and MESO based on COX analysis (P < 0.05)." (PMID 37561335, 2024). "In our study, we initially screened the prognostic marker role of TMEM44 in KIRC through pan-cancer survival analysis, and further investigation confirmed its significance." (PMID 37561335, 2024). "We demonstrated that knockdown of TMEM44 effectively slowed down the proliferation and migration of cancer cells, consistent with our bioinformatics analysis." (PMID 37561335, 2024). "Furthermore, disease-specific survival (DSS) analysis in pan-cancer indicated that TMEM44 acted as an independent predictor in ACC, KIRC, LGG, LIHC, LUSC, and MESO based on COX analysis (P < 0.05)." (PMID 37561335, 2024). "Moreover, after conducting overall survival (OS) analysis using COX analysis in pan-cancer, TMEM44 was identified as an independent prognostic factor in seven human tumors (ACC, COAD, KIRC, LGG, LIHC, LUAD, and MESO) (P < 0.05) (P < 0.05)." (PMID 37561335, 2024). "Based on the analysis of OS, PFS, and DSS of TMEM44 in pan-cancer, notable differences were observed in KIRC regarding high and low TMEM44 expression." (PMID 37561335, 2024). "We observed a significant upregulation of TMEM44 expression in KIRC, indicating its potential involvement in the pathogenesis of this cancer." (PMID 37561335, 2024). "The genes—including BEST4, LMO1, ARID3C, TMEM44, FKBP10, and TRIB3—were correlated with VSX1 and might play a primary role in the transcriptional misregulation of cancer from the TCGA database." (PMID 36463181, 2022).
tumor (2 papers, 2021 to 2024). "One limitation of this study is that we were unable to elucidate the underlying mechanism by which TMEM44 affects tumor progression." (PMID 37561335, 2024). "Although the function of TMEM44 remains poorly understood, our study and bioinformatics analysis suggest that TMEM44 can significantly influence tumor progression in KIRC and is an important member of the TMEM family." (PMID 37561335, 2024). "The EdU assay further confirmed that downregulation of TMEM44 expression in 786-O cells significantly affected tumor cell proliferation." (PMID 37561335, 2024). "As immune checkpoint inhibitors are a hot topic in tumor therapy, our correlation analysis of TMEM44 with selected immune checkpoints showed significant associations." (PMID 37561335, 2024). "Furthermore, through a comprehensive series of in vitro functional assays, we have elucidated the role of TMEM44 in promoting tumor development in KIRC." (PMID 37561335, 2024). "However, the specific role and mechanism of TMEM44 in tumor biology remain largely unexplored." (PMID 37561335, 2024). "The expression levels of TMEM44, TMEM67, CBX3, and ELOVL3 in tumor tissue were higher than in normal tissue, which was consistent with the trend in EC." (PMID 33463006, 2021). "The TMEM44 and TMEM67 were found to be significantly correlated with the tumor stage in EC." (PMID 33463006, 2021).
TMEM44 also shares sentences with these, for which no sentence is quoted: atherosclerosis (1 paper); breast carcinoma (1); lung carcinoma (1); schizophrenia (1).